BMP7 (bone morphogenetic protein 7)
Diseases named in the same sentence as BMP7 in open-access papers (continued):
Sharing a sentence is not in itself a finding about the gene and the disease.
diabetes (continued). "In another study, treatment with recombinant BMP7 protein in a rodent model of prediabetes, was able to confer improvements in diastolic function; in that study recombinant BMP7 protein administration commenced at the same time as induction of diabetes." (PMID 34690762, 2021). "In a pre-diabetic murine model of diabetes, BMP7 treatment elicited a beneficial impact on specific aspects of cardiac remodelling, namely cardiomyocyte apoptosis and cardiac fibrosis, which conferred improvements in cardiac function." (PMID 34690762, 2021). "In fact, levels of these endogenous BMP7 inhibitors are increased in diabetes, with tubule-specific knockdown of Gremlin conferring improvements in acute renal fibrosis." (PMID 34690762, 2021). "Following 18 weeks of untreated diabetes, mice were administered with a single tail-vein injection of recombinant adeno-associated viral vector (AAV), containing the BMP7 gene, or null vector." (PMID 34690762, 2021). "Reduction in BMP-7 expression is associated with various diseases including osteoporosis, CVD and diabetes." (PMID 31979268, 2020). "Studies from our laboratory correlated with these in vitro studies in that BMP-7 attenuates cardiac myocyte apoptosis in diabetes-induced mice." (PMID 31979268, 2020). "For example, BMP-7, which is found in human vascular calcification, slows the progression of arterial calcification in both human and mice with diabetes and hyperlipidemia." (PMID 31620082, 2019). "In vitro culture of human exocrine tissue or ductal cell lines with bone morphogenetic protein 7 (BMP7) or preadipocyte factor 1 (Pref-1) resulted in beta cells that were able to reverse diabetes when transplanted in diabetic mice." (PMID 29227863, 2017). "In this study, we demonstrate that sildenafil increases BMP7 expression in diabetes and that such effect occurs alongside the downregulation of miR-22, a known regulator of BMP7." (PMID 28294194, 2017). "Studies in humans and mice investigated BMP7 mRNA levels in various tissues and metabolic conditions such as obesity, diabetes, and the metabolic syndrome." (PMID 27340502, 2016). "Animal studies demonstrated that the renal BMP7 protected against DN, and the BMP7 partially reversed kidney hypertrophy induced by diabetes, urine albumin excretion, restoring GFR, as well as glomerular histology toward normal." (PMID 25359423, 2014). "Another example for a strong influence of diabetes state on adipokine relationships is BMP7 and DLK1, which clustered differentially in obese patients with or without T2D." (PMID 24968098, 2014). "This provides a novel insight into the role of BMP7 in skin wound healing in diabetes and it indicates that BMP7 may represent a potential therapeutic target for the treatment of DFUs." (PMID 40076659, 2025). "Moreover, the number of M2 macrophages and the M1/M2 ratio were evaluated to elucidate the immunomodulatory effect of BMP7 in wounds of animals with diabetes." (PMID 40076659, 2025). "The bone morphogenetic protein 7 (BMP-7) had been shown to inhibit inflammation-induced muscle atrophy and improve muscle dysfunction caused by streptozotocin (STZ)-induced diabetes, its mechanism of action remains unclear." (PMID 38313305, 2024). "Furthermore, given the much wider application potential of BMP-7 in conditions with huge global incidence—such as diabetes and obesity for example—pharmaceutical companies investing in BMP-7 will certainly earn significant return on investment." (PMID 37626268, 2023). "The GTT test revealed blood glucose levels, and the incremental glucose curve over time (60–120 min) was significantly reduced in the BMP-7 group as compared with untreated diabetes, suggesting BMP-7 treatment significantly ameliorated hyperglycemia (p < 0.05) in diabetic mice." (PMID 36829889, 2023). "Furthermore, of specific interest to the female bias in LN, in the commonly used db/db murine model of diabetes, female sex was linked to a significantly higher TGF-β/BMP-7 mRNA ratio." (PMID 37626268, 2023).
diabetes (continued). "Following the BMP-7 treatment, diabetic mice showed a significant increase (p < 0.05, ~82%) in body weight, suggesting BMP-7 treatment attenuates weight loss with the potential to improve metabolism in the setting of diabetes." (PMID 36829889, 2023). "Finally, heart function was measured using echocardiography to examine the diabetes-induced cardiomyopathy and the therapeutic effect of BMP-7 in improving heart functionality." (PMID 34685620, 2021). "These series of beneficial effects with BMP-7 in diabetic cardiomyopathy could make this osteoporosis drug a future added treatment to diabetes." (PMID 34685620, 2021). "Interestingly, a significant (p < 0.05) decrease in high-density lipoprotein cholesterol (HDL-C, ~28%) levels was observed in diabetic mice, whereas BMP-7 treatment significantly (p < 0.05) attenuated diabetes-induced LDL-C (~28%), TRG (~62%), and VLDL-C (~59%) increases." (PMID 36829889, 2023). "To determine the lipid accumulation and monocyte infiltration leading to increased inflammation, and whether BMP-7 treatment attenuates diabetes-induced inflammation, we performed a cytokine antibody array consisting of 96 proinflammatory and anti-inflammatory proteins." (PMID 36829889, 2023). "BMP7 is currently FDA-approved (marketed as OP-1 by Stryker Biotech), under the Humanitarian Device Exemption, for utilization in long bone nonunions and recalcitrant nonunions, but has not yet been used in human clinical trials as a weight-loss or anti-diabetes drug." (PMID 35646839, 2022). "Given the lack of studies exploring the potential protective actions of BMP7 in diabetes and/or cardiac pathologies, we sought to investigate whether manipulation of BMP7 signalling would confer an improvement on adverse cardiac remodelling in the diabetic heart." (PMID 34690762, 2021). "To investigate the effects of BMP7 on skin wound healing in diabetes, we used an excisional wound model in mice with STZ-induced diabetes." (PMID 40076659, 2025). "In another study, sulforaphane (SFN) treatment counteracted the diabetes-induced decline in H3K9/14Ac expression and H3K9/14Ac levels in the BMP-7 gene promoter, which was accompanied by BMP-7 upregulation." (PMID 36983082, 2023). "Diabetes induction increased serum levels of glucose, Cr, urea, MDA, and thiol, but decreased BMP7 and FRMD3 genes expression." (PMID 36945919, 2023). "Based on these data, we all but confirmed that USCs secreted exosomes carrying some BMP-7 and high levels of VEGF, TGF-β and angiogenin to be involved in renal protection in diabetes." (PMID 26852014, 2016). "In this article, we examined the expression pattern of 3 important proteins, BMP7, podocin, and THP, in the early stage of DN using a diabetic mouse model." (PMID 23573468, 2012). "In our study, the holistic approach, i.e., beyond single-group comparisons, revealed that the sex factor significantly influences the effect of diabetes on the expression of the acute phase protein SAA, the profibrotic transcription factor Snail1, and the TGF-β1/BMP7 ratio." (PMID 37109170, 2023). "Additionally, the expression level of MMP-9 reduced significantly following BMP-7 treatment, which suggests BMP-7 treatment decreased both vascular and interstitial fibrosis as well as extracellular profibrotic protein MMP-9 in the diabetes-induced muscle myopathy." (PMID 36829889, 2023). "Recently, we identified that bone morphogenetic protein-7 (BMP-7) reduced hyperglycemia and sarcopenia in diabetes, but whether BMP-7 could reduce diabetic cholesterol levels, potentially linked with inflammation, sarcopenia and adverse muscle remodeling, has not yet been addressed." (PMID 36829889, 2023). "Therefore, the BMP family may be an exciting prospect for future treatments of diabetes as BMP2, BMP6, BMP7, and BMP 9 have function of improving glucose metabolism." (PMID 34258293, 2021).
diabetes (continued). "It is also not yet clear whether a single dose of BMP-7 is enough to decrease diabetes and diabetic cardiomyopathy as long-term studies are not well established." (PMID 31979268, 2020). "Given the lack of studies assessing the potential protective actions of BMP7 in diabetic complications, particularly in DFU, we sought to investigate whether this treatment would confer an improvement on wound healing by using a streptozotocin (STZ)-induced diabetes animal model of wound healing." (PMID 40076659, 2025). "The current literature has suggested the therapeutic efficacy of BMP-7 mediated through canonical and non-canonical mechanistic pathways in various animal disease models of CVD, diabetes and obesity." (PMID 31979268, 2020).
diabetic nephropathy (34 papers, 2010 to 2023). "Loss of BMP-7 signaling activity, as illustrated by lower phosphorylated Smad 5 protein level, was observed in experimental diabetic nephropathy." (PMID 20661431, 2010). "In cultured tubular cells, TGF-βdecreases BMP-7 expression, which suggests that a rise in tubular TGF-β levels during the evolution of diabetic nephropathy contributes causally to the loss of BMP7 and BMP7 type I and II receptors." (PMID 20661431, 2010). "In experimental models of diabetic nephropathy, a decreased expression of BMP-7 was found in mesangial cells and renal tissues." (PMID 36836700, 2023). "BMP7 impedes the progression of diabetic nephropathy by inhibiting the canonical TGF-β pathway, attenuating ferroptosis, and helping regenerate diabetic pancreas." (PMID 37293506, 2023). "A high level of BMP-7 expression in proximal tubules and podocytes was revealed at the early stages of human diabetic nephropathy; however, low expression of BMP-7 was found at advanced stages of the disease." (PMID 36836700, 2023). "Elevated production of BMP-7 in renal tissues was demonstrated previously at the early stages of diabetic nephropathy and under statin treatment." (PMID 36836700, 2023). "This study aimed to investigate the precise role and potential molecular mechanisms of BMP-7 in the progression of diabetic nephropathy." (PMID 35721136, 2022). "In a mouse model of streptozocin-induced diabetic kidney disease, overexpression of BMP-7 through plasmid transfer activated the Smad 1/5 signaling pathway and thereby alleviated epithelial–mesenchymal transition and kidney fibrosis." (PMID 36558936, 2022). "In experimental systems, BMP-7 recombinant protein expression or overexpression inhibits fibrosis in diabetic nephropathy or AKI, TGF-β-initiated EMT and E-cadherin suppression." (PMID 31801572, 2019). "Under disease conditions, expression of renal BMP-7 was significantly down-regulated, as detected in diabetic nephropathy and ischaemic acute kidney injury." (PMID 27145860, 2016). "In this model, it was found that BMP-7 administration delayed the onset of diabetic nephropathy and prevented glomerulosclerosis; and even partially reversed diabetic kidney hypertrophy and restored GFR in the progression stage of DN." (PMID 25954203, 2015). "Under several disease states like ischemia-reperfusion injury, diabetic nephropathy, and hypertensive nephrosclerosis, BMP-7 has been reported to be down-regulated in the kidney, and increased again during the regenerative phase." (PMID 25954203, 2015). "BMP-7 expression is reduced in both animal models of diabetic nephropathy (DN) and in DN patients, and is also downregulated in the rodent model of ischemic acute tubular necrosis." (PMID 25972814, 2015). "BMP-7 and Gremlin are involved in renal development and diabetic nephropathy and undergo expression changes in the diabetic kidney." (PMID 25834571, 2015). "The aim of this study was to determine the diagnostic values of kidney shear wave velocity (SWV) and bone morphogenetic protein-7 (BMP-7), and their correlation in the diagnosis of early diabetic kidney disease." (PMID 25790348, 2015). "Dolan and colleagues proposed that reactivation of Gremlin (and BMP-7) in the diabetic kidney is a novel therapeutic target for diabetic nephropathy, since administration of the Gremlin ligand BMP-7 is protective in models of progressive renal diseases." (PMID 25834571, 2015). "Consistent with its TGF-β antagonizing role, exogenous recombinant BMP-7 administration in vivo led to significant reduction of renal fibrosis in pre-clinical models of diabetic nephropathy and CKD." (PMID 25972814, 2015). "While several authors have shown that this pathway is antifibrotic when is induced by BMP-7, others have shown a pro-fibrotic role, especially in diabetic nephropathy and also in dermal sclerosis." (PMID 25313562, 2014).
diabetic nephropathy (continued). "To identify the critical molecular regulators in the early stage of diabetic nephropathy, we studied the expression of BMP7 and 2 important kidney-specific markers, podocin and Tamm–Horsfall protein (THP)." (PMID 23573468, 2012). "The renal protective protein, bone morphogenetic protein-7 (BMP-7), can reduce glomerular and tubulointerstitial fibrosis and prevent the pathogenesis in diabetic nephropathy." (PMID 22474533, 2012). "Our results are in accordance with findings in animals, where the renal BMP-7 expression was reduced in several kidney disease models, including acute ischemic renal injury, tubulointerstitial fibrosis and diabetic nephropathy." (PMID 21080950, 2010). "A significant reduction in BMP-7 expression at the late stage of diabetic nephropathy has been reported." (PMID 20661431, 2010). "Besides, the roles of BMP7 in inflammatory responses in diabetic kidney disease have also been extensively explored." (PMID 36858954, 2023). "Recently, a small molecule (AA123), which exerts BMP-7 mimetic activity by activating activin-like kinase 3 signaling, exhibited antifibrotic activity in murine models of nephrotoxic serum-induced chronic kidney fibrosis and diabetic nephropathy." (PMID 36558936, 2022). "Importantly, in the kidney, overexpression of BMP7 in transgenic mice protects against the development of diabetic nephropathy." (PMID 34690762, 2021). "Moreover, studies on BMP-7 attenuating diabetic nephropathy and atherosclerosis are gaining significant attention in the current literature due to BMP-7 being a commonly used clinical drug to treat patients with osteoporosis and nonunion bone fracture." (PMID 34685620, 2021). "In addition, BMP7 overexpression attenuated oxidative stress and inflammatory responses in diabetic kidney disease." (PMID 34801077, 2021). "Whereas TGF-β is a major biological signal that initiates a pro-fibrotic response, BMP7 appears to counterbalance these actions, and may in fact be antifibrogenic, restoring vascular stability and limiting capillary rarefaction in diabetic nephropathy." (PMID 34690762, 2021). "In recent years, recombinant BMP7 emerged as a potential therapy against diabetic nephropathy." (PMID 31561501, 2019). "Renal changes in diabetes nephropathy are also associated with down-regulation of bone morphogenic protein (BMP) receptor function and TGF-β mediated transcription factor production and supply of BMP-7 restores function." (PMID 31277442, 2019). "Moreover, BMP7 has antifibrotic activity, which prevents ureteral obstruction and diabetic nephropathy." (PMID 31561501, 2019). "Furthermore, clinical trials of BMP-7 analog THR-V-123 has been launched by Thrasos to study its efficacy on diabetic nephropathy, which results worth anticipated." (PMID 25954203, 2015). "The determination of SWV together with serum BMP-7 may play an important role in the diagnosis of diabetic kidney disease." (PMID 25790348, 2015). "Bone morphogenetic protein-7 (BMP-7) could reduce glomerular and tubulointerstitial fibrosis and prevent the pathogenesis in diabetic nephropathy." (PMID 21876712, 2011). "We conclude that inhibition of Gremlin exerts beneficial effects on the diabetic kidney mainly through maintenance of BMP-7 activity and that Gremlin may serve as a novel therapeutic target in the management of diabetic nephropathy." (PMID 20661431, 2010). "A specific question should be addressed whether Gremlin has BMP-7-independent effects on the pathogenesis of diabetic nephropathy." (PMID 20661431, 2010). "Morrissey and associates showed that exogenously administered recombinant human (rh) BMP-7 may even resolve, at least partially, glomerular and interstitial fibrosis in experimental diabetic nephropathy." (PMID 20661431, 2010). "BMP-7, a member of the TGF-β superfamily, demonstrated an anti-fibrotic effect in diabetic nephropathy." (PMID 36836700, 2023).
diabetic nephropathy (continued). "The expression of BMP7 was significantly downregulated, while the expression of THP was increased in the early stage of diabetic nephropathy." (PMID 23573468, 2012). "Expression levels of TGF-β1, fibronectin, collagen IV, and BMP-7 as well as antioxidative effects of XCHT treatment were examined in order to explore the renal protective effect and mechanism of XCHT in diabetic nephropathy." (PMID 22474533, 2012). "In summary, BMP-7 has a negative role in regulating EMT in renal tubular epithelial cells in diabetic nephropathy." (PMID 35721136, 2022). "Efficacy of BMP7 therapy without altering TGFβ signaling has been reported previously in a model of diabetic nephropathy." (PMID 27766493, 2017). "In addition, losses of tubular BMP-7 or serum BMP-7 have been observed in progressive diabetic nephropathy or in direct correlation with a loss of viable renal mass, indicating that BMP-7 plays an important role in the pathogenesis of DKD." (PMID 25790348, 2015). "Administration of exogenous BMP-7 or its overexpression alleviates kidney fibrosis in several CKD experimental models, including genetic models of kidney fibrosis (Alport syndrome and lupus nephritis-like glomerulonephritis), unilateral ureteral obstruction (UUO), and diabetic nephropathy." (PMID 36558936, 2022). "In a model of diabetic nephropathy, urinary progenitor-secreted exosomes were found to reduce podocyte apoptosis by suppressing caspase-3 and promoting vascular regeneration, which may be related with the cytokines VEGF, TGF-β1, angiogenin and BMP-7 contained in urinary progenitor-derived exosomes." (PMID 33401654, 2021).